VWF (von Willebrand factor)
Diseases named in the same sentence as VWF in open-access papers (continued):
Sharing a sentence is not in itself a finding about the gene and the disease.
cardiovascular disease (continued). "Exercise could increase the release of vWF by sympathetic activation, and vWF has been proven to be associated with cardiovascular diseases, particularly exercise-induced pathological outcomes." (PMID 34682364, 2021). "Given that low VWF has been reported in a great number of the general population, and that high VWF levels are associated with high risk of cardiovascular disease, it would have been essential to know what the levels are in the control and CAD groups of the study." (PMID 33448867, 2021). "This might pave a way to new approaches to measure vWF function, which eventually might turn vWF into a treatment target or an important tool for diagnostics and risk assessment in cardiovascular disease." (PMID 33096906, 2020). "The proposed mechanism believed to underlie how ABO blood group may influence cardiovascular disease risk involves the possible regulatory effect of ABO antigens on plasma levels of von Willebrand factor (VWF) and coagulation factor VIII (FVIII)." (PMID 29780641, 2018). "Non-O blood groups have an increased mortality, particularly due to cardiovascular diseases, which may be due to the effect of blood group alleles on blood biochemistry or their effect on von Willebrand factor and factor VIII levels." (PMID 25592833, 2015). "A decrease in the blood vWF may reduce the risk of cardiovascular disorders." (PMID 35174782, 2022). "Furthermore, parameters that correlated with the levels of indoxyl sulfate (von Willebrand factor, soluble urokinase-type plasminogen activator receptor, soluble intercellular adhesion molecule-1) were positively associated with the prevalence of cardiovascular disease in a CKD patients." (PMID 28122514, 2017). "The observed vWF-ADAMTS13 axis dysregulation supports the rationale for investigating vWF-targeted therapeutics, including agents such as caplacizumab, in cardiovascular disease management." (PMID 41007843, 2025). "In patients with these cardiovascular diseases excessive high shear stress is generated in the bloodstream, where the cleavage of high molecular weight VWF multimers is enhanced." (PMID 38268521, 2024). "High plasma levels of sP-selectin are correlated with the severity of cardiovascular disease in humans, similar to VWF." (PMID 38203218, 2023). "Fibrinogen, vWF, and ADAMTS13 play important roles in both coagulation and inflammation, and have been reported as independent risk factors for cardiovascular disease." (PMID 34559294, 2022). "It has been suggested that directly limiting vWF release from WPBs has the potential as a therapeutic for cardiovascular disease." (PMID 35456570, 2022). "For a better understanding of the role of this interaction in cardiovascular disease, molecules are needed to specifically interfere with the opened VWF A1 domain interaction with GPIbα." (PMID 35216161, 2022). "During the 2 years of follow-up, 78 (42.6%) patients in the AMI group experienced MACEs, and more patients died from cardiovascular disease in the patient group with higher VWF: Ag levels." (PMID 36684571, 2022). "The imbalance levels of ADAMTS13 and VWF in circulation will lead to the occurrence of cardiovascular disease." (PMID 35155621, 2021). "Another study confirmed that VWF and fibrinogen mediate up to 10% of the association between FT4 and cardiovascular disease." (PMID 34395522, 2021). "Many recent studies have demonstrated that high vWF levels are a powerful prognostic maker in subjects with cardiovascular diseases." (PMID 29409455, 2018). "Specific VWF antagonism represents a new interesting issue in thromboinflammation therapy with a potential role in metabolic and cardiovascular disease." (PMID 28634421, 2017). "A chronically elevated level of von Willebrand factor (vWF) is a common finding in patients with cardiovascular diseases." (PMID 28570705, 2017).
cardiovascular disease (continued). "While in the general population, the association between vWF and thromboembolic cardiovascular events is weak, in patients with a pre-existing cardiovascular disease, the level of vWF can be used to predict adverse cardiovascular events." (PMID 28570705, 2017). "This SNP was highly associated with vWF and FVIII in the discovery phase, and this observation throws light on possible mechanisms underlying end-stage coagulation in cardiovascular disease." (PMID 23381943, 2013). "Researchers have expressed concern about whether ADAMTS13 and VWF had a co-effect on cardiovascular disease." (PMID 34276770, 2021). "Further studies will be required to define whether inter-individual variations in ABO(H) expression on platelets and/or VWF (particularly HXP and LXP) impact upon risk for cardiovascular disease." (PMID 33110150, 2020). "Improved understanding of VWF-mediated hemostasis and thrombosis in all such animals will continue to contribute to better modeling and understanding of human bleeding, thrombotic, and cardiovascular diseases." (PMID 22091368, 2010). "VWF has effects that are largely unaffected by other cardiovascular disease risk factors, unlike ADAMTS-13, which appears to have effects that are masked by the coexistence of other risk factors." (PMID 18194418, 2008). "However, patients with cardiovascular disease showed an increased coagulation potential both at rest and after exercise compared to healthy subjects, involving elevated thrombin–antithrombin complexes and von Willebrand factor." (PMID 39457580, 2024). "Thus, the role of VWF in cardiovascular disease needs further investigation." (PMID 34276770, 2021). "In a large, multiethnic cohort free of cardiovascular disease and with a spectrum of kidney function ranging from normal to moderate CKD, even small decrements in eGFR were associated with significantly higher levels of sTM, sTF, D-Dimer, vWF, factor VIII, PAP and TFPI." (PMID 21269477, 2011). "Both markers have been related to cardiovascular disease (CVD).We aimed to investigate the influence of ADAMTS13 single nucleotidepolymorphisms (SNPs) on levels of ADAMTS13 and VWF, and CVD." (PMID 36474435, 2022). "Long term prospective trials at large scale are required to explore the predictive role of VWF and ADAMTS13 in cardiovascular diseases." (PMID 32095288, 2020). "The dynamics of both VWF and ADAMTS‐13 are of potential importance in cardiovascular diseases and their management." (PMID 29108103, 2018). "However, in non-septic patients with risk factors for cardiovascular disease, vWF is raised, correlates with endothelial activation as measured by E-selectin, and is inversely proportional to endothelial NO bioavailability as estimated by flow-mediated dilatation of the brachial artery." (PMID 20482750, 2010). "Specifically, higher levels of factor VIII (FVIII) and von Willebrand factor (vWF) observed in individuals with a non-O blood group have been suggested to affect the development of cardiovascular disease." (PMID 36892462, 2023). "More importantly, both ratios of VWF:Plasminogen and SerpinC1:Plasminogen were associated with reverse LV remodeling in post-AMI patients, independent of other cardiovascular disease risk factors." (PMID 36613770, 2022). "The activation of vWF and its counterbalance by ADAMTS-13, the vWF-cleaving protease, might contribute to complications of cardiovascular diseases." (PMID 33096906, 2020).
infection (95 papers, 2007 to 2026). The state of being infected such as from the introduction of a foreign agent such as serum, vaccine, antigenic substance or organism. "The BBB water exchange rate during infection was associated with higher levels of plasma von Willebrand factor (VWF), a marker of acute vascular inflammation." (PMID 37013549, 2023). "VWF is an acute-phase protein and its deficiency in mild forms of VWD presenting with borderline VWF levels can be masked due to the effects of age, stress, infection, or physical activity." (PMID 35505650, 2022). "The fungus Mycosphaerella graminicola (Septoria tritici) is known to have high levels of expression for von Willebrand factor annotated transcripts related to cellular adhesion during infection, where it causes leaf blotch of wheat." (PMID 33925458, 2021). "The observation of similarities between the association of CD with VWF-release, and symptoms induced by bacterial infections initiated an increasing need to develop infection models and sophisticated visualization techniques in the last decade." (PMID 33015097, 2020). "Moreover, as VWF is also associated with increased inflammation, we monitored changes in cytokine expression following infection." (PMID 37222614, 2023). "Furthermore, the infection causes the release of von Willebrand factor (VWF), which plays a role in platelet activation and thrombus formation." (PMID 33948415, 2021). "Previous studies have confirmed that higher plasma levels of VWF or VWF antigen (VWF:Ag) have been associated with a more severe clinical presentation in the acute phase and may remain elevated several months after infection." (PMID 40725101, 2025). "We find that an increase in BBB water permeability during infection is associated with higher levels of plasma von Willebrand factor, a marker of vascular inflammation, and that infection leads to higher levels of astrocytic AQP4 which may drive the observed increases in BBB water exchange." (PMID 37013549, 2023). "Interestingly, counts remained high for both infections in vWF-deficient mice." (PMID 33203754, 2020). "Stratified analyses indicate that VWF and factor VIII are more strongly associated with CIS in the presence of recent infections." (PMID 41841261, 2026). "Infections, particularly those that induce systemic inflammation, can alter vWF levels, potentially contributing to disease complications." (PMID 40283058, 2025). "The surface-associated proteins possessed by S. aureus to bind to host fibrinogen, fibronectin, collagen, and von willebrand factor, thus enabling the bacteria to colonize and establish a focus of infection." (PMID 40588743, 2025). "This study aimed to compare vWF levels between Plasmodium-infected and uninfected individuals and assess changes in severe infections." (PMID 40283058, 2025). "We also detected the Von Willebrand factor (vWF) after infection, indicating vascular activation after injury." (PMID 38627497, 2024). "One found that von Wildebrand factor (vWf) levels, a clotting factor, increased in the decidual and chorionic villi endothelium with infection." (PMID 36952548, 2023). "Contrarily, Fibrinogen, FVIII, VWF and Rcof were elevated in the infection group (acute phase) compared to controls and the difference was statistically significant." (PMID 37886991, 2023). "VWF and Rcof remained elevated post infection compared to controls and the difference was statistically significant." (PMID 37886991, 2023). "The severity of infection as assessed by nSOFA score was positively correlated with VWF levels in the acute phase of infection (r = 0.598, p = 0.014) and negatively correlated with ADAMTS-13 levels at the same time point (r = −0.531, p = 0.034)." (PMID 37886991, 2023). "Within 4 hours of infection, WT mice developed increased vWF deposition compared with VE-Cad ADAM10–/– mice preceding the difference in platelet aggregation seen at 6–8 hours." (PMID 37788087, 2023).
infection (continued). "In return, these cells exhibited a massive release of von Willebrand factor (vWF) within two hours post-infection as well as vascular cell adhesion molecule-1 (VCAM-1), which is an another platelet adhesion protein." (PMID 36768333, 2023). "BBB water exchange during the infection estimated using the CCXR model showed a strong correlation with plasma VWF levels, a marker of vascular inflammation." (PMID 37013549, 2023). "Endothelial activation during infection leads to release of VWF in large amounts, promoting aggregation of platelets, granulocytes and monocytes, as well as adhesion of bacteria like Staphylococcus aureus." (PMID 37886991, 2023). "On the other hand, levels of fibrinogen, factor VIII (FVIII) and VWF were significantly higher in the acute phase in comparison to controls and recovery, while they remained persistently higher in the infection group compared to controls." (PMID 37886991, 2023). "Hemocytin, an orthologs of Drosophila hemolectin and human von Willebrand factor, is an adhesive protein released from the granules of granulocytic hemocytes via exocytosis and is the first step in the formation of nodules after infection." (PMID 38274813, 2023). "Vascular endothelial cells contain unique secretory organelles, the Weibel–Palade bodies (WPB), which store the adhesion receptors P-selectin and von Willebrand factor (VWF) and respond to vascular injury and infection by regulated exocytosis." (PMID 35084586, 2022). "Direct infection of vascular endothelial cells increases the release of von Willebrand factor and expression of TF." (PMID 35948984, 2022). "Using RNAscope ISH technology, we found significantly more blood vessels expressing VWF messenger RNA (mRNA) in the lung vascular architecture of SARS–CoV-2–infected WT mice when compared to Casp11−/− lungs at day 4 after infection." (PMID 35588457, 2022). "Studies also revealed that VWF is able to directly bind to Staphylococcus aureus in blood under shear stress and promote intravascular infection of the sub-endothelium." (PMID 34095003, 2021). "In vitro germination assay and infection assay proved that E. hellem significantly increased the rates of germination and infection, and these effects would be reversed by VWF blocking antibody." (PMID 34095003, 2021). "Our findings demonstrated that VWF can bind microsporidia in circulation, and modulate its pathogenicity, including promoting germination and infection rate." (PMID 34095003, 2021). "Deeper insight into the pathophysiological consequences of the pneumococcus interaction with VWF was also provided by infection analyses using zebrafish larvae." (PMID 33015097, 2020). "the possible mechanisms of infection are adsorption of vWF onto plasma cells or activated platelets apart from the presence of vWF-specific antibodies and inhibitors." (PMID 31855136, 2020). "Microscopic real-time visualization of larval infection confirmed the recruitment of endothelial-derived VWF to circulating pneumococci and VWF-mediated attachment to the endothelial vessel walls." (PMID 33015097, 2020). "Direct infection of vascular endothelial cells has been demonstrated to increase the release of von Willebrand factor and increase cell-surface expression of tissue factor." (PMID 33489573, 2020). "Binding of platelets to Kupffer cells in the liver of mice following infection with B. cereus or S. aureus is mediated by VWF." (PMID 32314961, 2020). "Among the early response proteins in plasma, eight showed differential abundance as early as 6 h post-infection, and these included haptoglobin, Serpin A3-6, Serpin A3-8, vWF, LBP, sCD14, MBL1, and APOA4." (PMID 31803186, 2019). "By contrast, enteral feeding reduced the level of vWF, a coagulation factor, as early as 6 h after infection." (PMID 31803186, 2019).
infection (continued). "Our cell culture infection analyses with pneumococci showed a dose-dependent VWF-mediated adherence to HUVECs, which prompted us to designate VWF as a novel adhesion cofactor for pneumococcal attachment to the endothelium." (PMID 30972039, 2019). "In regard of these coherences, we wanted to analyse the interaction of pneumococci with VWF in a complex living system and performed infection analyses with Danio rerio larvae as in vivo model of a complete blood environment." (PMID 30972039, 2019). "Cellular infection analyses demonstrated that S. pneumoniae adherence to endothelial cells induces the release of high amounts of VWF from Weibel Palade Bodies into the cell media." (PMID 30972039, 2019). "However, while this assumption is true for the present IE experimental model, where pre-existing physical valve damage is the nidus of infection, it might be different in other scenarios, such as minimal endothelial lesions, which are associated with the presence of high VWF levels." (PMID 30280967, 2018). "Together, this highlights a role of vWF after infection with different pathogens particularly in the CNS." (PMID 27224245, 2016). "We expected the increased platelet binding to co-occur with increased VWF production, as a general inflammatory response during infection." (PMID 25852676, 2015). "Upon a stimulus, for example an infection, this balance is changed into a procoagulant state by release of amongst others vWF and expression of PAI-1." (PMID 24502801, 2014). "HPAI-H5N1 virus infected animals showed trends of increased VWF activity early after infection with highest levels seen at 1 (p = <0.05) and 2 dpi (p = <0.05)." (PMID 24884666, 2014). "In HPAI-H5N1- and pH1N1 virus infected animals VWF activity increased in the first two days after infection, coinciding with peak virus titers." (PMID 24884666, 2014). "Von Willebrand factor activity levels increased early in infection suggesting endothelial cell activation." (PMID 24884666, 2014). "A recent study performed in human volunteers demonstrated that vWF and vWF propeptide release from the Weibel–Palade bodies were significantly increased early in P. falciparum blood-stage infection, implying acute endothelial activation." (PMID 19450727, 2009). "Subsequently, a study of 14 healthy volunteers infected with P. falciparum showed that the increased plasma VWF and VWF propeptide levels develop soon after the onset of blood stage infection." (PMID 19300493, 2009). "Given the pivotal role of endothelial injury in ACLF pathogenesis, biomarkers such as vWF and ADAMTS13 may enhance risk stratification and enable earlier interventions, including infection prevention, trial enrollment, and timely liver transplant evaluation." (PMID 40429533, 2025). "However, post-infection downregulation was observed, likely due to tachyzoites or altered VWF expression, though undetectable VWF levels prevented further analysis." (PMID 40141288, 2025). "This may reflect secondary consumption due to excessive release of vWF–which has been consistently shown to be markedly raised in the infection." (PMID 37448794, 2023). "Aims of the present study were to investigate whether FVIII, Willebrand (VWF) Antigen (Ag) and ristocetin-cofactor (VWF:RCo) predicted adverse outcomes in pregnant women with infection by SARS-Cov-2 infection." (PMID 35189860, 2022). "During infection, inflammation may regulate the formation of VWF-platelet thrombi in large arteries and small blood vessels by increasing VWF levels, enhancing VWF responsiveness and regulating the level and activity of regulatory molecules in the circulation." (PMID 35139909, 2022). "Weibel–Palade bodies are secretory organelles in endothelial cells with high concentrations of von Willebrand factor (VWF), P-selectin, IL-8, IL-6, angiopoietin-2, and monocyte chemoattractant protein-1 alerting and recruiting platelets and neutrophils to the site of infection/inflammation." (PMID 35186793, 2022).